STARD13 (StAR related lipid transfer domain containing 13)
Description:
GTPase-activating protein for RhoA, and perhaps for Cdc42. May be involved in regulation of cytoskeletal reorganization, cell proliferation and cell motility. Acts a tumor suppressor in hepatocellular carcinoma cells.
Synonyms: DLC2; GT650; ARHGAP37; LINC00464
Tractability: Small molecule: it has a high-quality binding pocket. Antibody: UniProt places it where antibodies can reach, with medium confidence. PROTAC: ubiquitination databases record sites on it.
Gene: Protein-coding gene on chromosome 13 (33,103,137 to 33,350,630, reverse strand). Ensembl gene ENSG00000133121.
Subcellular location: Cytoplasm; Membrane; Mitochondrion membrane; Lipid droplet
Subcellular location (Human Protein Atlas): Golgi apparatus; Vesicles; Nucleoplasm
Pathways (Reactome):
Signal Transduction: CDC42 GTPase cycle; RHOA GTPase cycle; RHOB GTPase cycle; RHOC GTPase cycle
Gene Ontology:
Molecular function: protein binding; GTPase activator activity; lipid binding
Biological process: endothelial cell migration; endothelial tube lumen extension; negative regulation of cell migration involved in sprouting angiogenesis; actin cytoskeleton organization; regulation of Rho protein signal transduction; regulation of small GTPase mediated signal transduction; negative regulation of cell migration; signal transduction
Cellular component: cytosol; cytoplasm; lipid droplet; membrane; mitochondrial membrane
Genetic constraint (gnomAD): Loss-of-function variants: 59 observed, 103.8 expected, observed/expected ratio (o/e) 0.57, 90% interval 0.46 to 0.71. The upper end of that interval is the gene's LOEUF score, 0.71, which puts it in group 2 of 6, group 1 being the genes least tolerant of losing a copy. Missense variants: 1,370 observed, 1,452.9 expected, observed/expected ratio (o/e) 0.94, 90% interval 0.9 to 0.99. Synonymous variants: 561 observed, 560.37 expected, observed/expected ratio (o/e) 1, 90% interval 0.93 to 1.07.
Homologues: Orthologues: chimpanzee STARD13 (99% identical), macaque STARD13 (99% identical), guinea pig STARD13 (91% identical), dog STARD13 (90% identical), mouse Stard13 (90% identical), rat Stard13 (88% identical), rabbit STARD13 (88% identical), tropical clawed frog stard13 (69% identical), zebrafish stard13b (65% identical), zebrafish stard13a (65% identical), Caenorhabditis elegans gei-1 (28% identical). Paralogues in human: DLC1 (54% identical), STARD8 (44% identical).
Diseases named in the same sentence as STARD13 in open-access papers:
STARD13 is named in the same sentence as 52 diseases in open-access papers, as found by Europe PMC text mining. Sharing a sentence is not in itself a finding about the gene and the disease. The quoted sentences say what the papers report.
breast cancer (37 papers, 2012 to 2025). A primary or metastatic malignant neoplasm involving the breast. "A homozygote or heterozygote loss of StarD13 in mammary tumors linked to ErbB2 (tyrosine phosphate -receptor), increased lung metastasis in vivo as well, further demonstrating StarD13 invasion and metastasis suppressor functions." (PMID 32900380, 2020). "In addition, Kaplan-Meier survival analysis reveals that mRNA level of STARD13 and its ceRNAs is remarkably associated with survival of breast cancer patients." (PMID 26985770, 2016). "miR-21 is an established oncogenic miRNA exerting its suppressive activities on key tumor suppressive targets such as StAR Related Lipid Transfer Domain Containing 13 (STARD13) and Zinc Finger Protein 132 (ZNF132) as implicated in breast cancer." (PMID 40863728, 2025). "Tanshinone IIA attenuated the stemness and enhanced adriamycin sensitivity of breast cancer cells by regulating the miR-125b/STARD13 axis." (PMID 40260390, 2025). "The potential mechanisms by which the STARD13 and other genes of this network inhibit breast cancer metastasis is that 3’ untranslated region (UTRs) of these genes have numerous miRNA binding sites and inhibit these miRNAs." (PMID 39170516, 2024). "Currently, we demonstrate that the inhibition on the miR-125b/STARD13 axis mediated by Tanshinone IIA attenuates breast cancer stemness and adriamycin sensitivity, providing new clues for breast cancer treatment." (PMID 35057866, 2022). "The study has previously revealed that miR-125b faciliates cell migratory ability breast cancer via targeting STARD13 (StAR-related lipid transfer protein 13)." (PMID 35057866, 2022). "This was surprising since previous reports from studies performed in astrocytoma, breast cancer, colon cancer and lung cancer, showed that StarD13 depletion inhibited cancer cell migration due to the dysregulation of RhoA activation." (PMID 34958986, 2022). "We and others have established the promoting effects of miR-125b/STARD13 axis in the progression of breast cancer and that STARD13 is critical for suppressing breast cancer stemness." (PMID 35057866, 2022). "Previous studies have demonstrated that STARD13 acts as a crucial tumor suppressor gene in cancer, such as prostate cancer, colon cancer, breast cancer, and lung cancer." (PMID 36241975, 2022). "Reversely, we further showed that the 3'UTR of STARD13 mRNA reduces the migratory ability of breast cancer cells via regulating miR-125b activity." (PMID 35057866, 2022). "It is also known that TP53INP1 and STARD13 have competitive endogenous RNA (ceRNA) interactions as both competitively bind to miR‐125b in the metastatic regulation of breast cancer." (PMID 33332677, 2021). "Known targets of miR-720 include TWIST1 in breast cancer, Rab35 in cervical cancer, StarD13 in colorectal cancer, and CCND1 in pancreatic cancer." (PMID 33880375, 2021). "Work by Xiaoman indicates that CDH5 can suppress the metastasis of breast cancer owing to the ability of its 3’-UTR serve as a ceRNA for STARD13." (PMID 33075110, 2020). "We have confirmed the tumor suppressor function of StarD13 in a wide array of cancers including, breast cancer, colon cancer and astrocytoma." (PMID 32900380, 2020). "A previous study reported that the StarD13-correlated ceRNA network suppressed breast cancer migration, invasion and EMT." (PMID 30899277, 2019). "Taken together, these results indicate that STARD13-correlated ceRNA network inhibits the tumor initiation ability of breast cancer." (PMID 29848346, 2018). "MiRNA-125b was shown to induce metastasis in MCF-7 and MDA-MB-231 breast cancer cells through targeting of STARD13." (PMID 30445766, 2018). "We have established the inhibitory role of STARD13-correlated ceRNA network in conferring CSC traits to breast cancer cells." (PMID 29848346, 2018). "Mechanistically, we found that activation of STARD13-correlated ceRNA network was negatively correlated with YAP/TAZ activity in breast cancer." (PMID 29848346, 2018).
breast cancer (continued). "To explore the related mechanisms contributing to STARD13-correlated ceRNA network in prohibiting breast cancer CSC formation, we tried to characterize the pathways regulated by STARD13-correlated ceRNA network." (PMID 29848346, 2018). "By constructing STARD13-correlated ceRNA 3′UTR stable overexpression or knockdown breast cancer cells, we aimed to explore the effects of STARD13-correlated ceRNA network on breast cancer stemness in vitro and in vivo." (PMID 29848346, 2018). "Our results uncover a novel mechanism of YAP/TAZ activation in breast cancer and propose the possibility to drive STARD13-correlated ceRNA network to inhibit breast cancer stem cell traits." (PMID 29848346, 2018). "Overall, these data indicated that mRNA levels of STARD13 and its ceRNAs were remarkably correlated with the survival of breast cancer patients." (PMID 26985770, 2016). "The KM plotter tool was employed to assess if mRNA levels of STARD13 and its ceRNAs correlated with the survival of breast cancer patients." (PMID 26985770, 2016). "To elucidate the potential mechanisms by which the STARD13 3’UTR inhibits breast cancer metastasis, we have applied an integrated computational and experimental approach in the present study." (PMID 26985770, 2016). "Our studies further show that STARD13 ceRNAs display concordant expression patterns with STARD13 in differently metastatic breast cancer cells, supporting that they all have strong sponging effects and intense reciprocal ceRNAs interaction." (PMID 26985770, 2016). "Collectively, these observations demonstrated that STARD13- and its ceRNAs-3’UTRs inhibited breast cancer metastasis in vitro." (PMID 26985770, 2016). "Altogether, these observations indicated that STARD13- and its ceRNAs-3’UTRs restrained breast cancer metastasis by inhibiting EMT process." (PMID 26985770, 2016). "Here, we identify CDH5, HOXD1, and HOXD10 as putative STARD13 ceRNAs and they display concordant patterns with STARD13 in different metastatic potential breast cancer cell lines and tissues." (PMID 26985770, 2016). "In the present study, we have discovered that ectopic expression of STARD13- and its ceRNAs-3’UTRs strongly suppresses breast cancer metastasis in vitro via inhibiting EMT." (PMID 26985770, 2016). "In the present study, we opted to characterize StarD13 in breast cancer in terms of expression, effect on cell proliferation and viability, GAP activity and role in motility and invasion." (PMID 24627003, 2014). "While examining the role of StarD13 in cell motility, we found that the knockdown of StarD13 in breast cancer cell lines inhibited cell motility." (PMID 24627003, 2014). "In the present study, we examined the role of StarD13 in breast cancer cell proliferation and motility." (PMID 24627003, 2014). "Looking at the effect of StarD13 knockdown on the adhesion of breast cancer cells to collagen, our results show that cells with StarD13 knockdown have increased adhesion to collagen by >2-fold as compared to control cells." (PMID 24627003, 2014). "This was consistent with the fact that although StarD13 was indeed a tumor suppressor in our breast cancer cells, as seen by its effect on cell proliferation, it was needed for cancer cell motility." (PMID 24627003, 2014). "In this study we aimed at characterizing StarD13 in breast cancer in terms of its level of expression and its role in cellular proliferation, motility and invasion." (PMID 24627003, 2014). "The level of expression of StarD13 was determined in patient tissues representing different grades of breast cancer compared to normal tissues." (PMID 24627003, 2014). "Before studying the role of StarD13 in breast cancer cells, we first wanted to investigate its level of expression in human breast cancer tissues." (PMID 24627003, 2014).
breast cancer (continued). "In order to supplement our results, we mined the oncomine database for microarray analysis where they measured StarD13 mRNA expression levels from 60 breast cancer samples grouped by grade." (PMID 24627003, 2014). "It showed that there were significant inverse correlations between the expression of miR-125b and STARD13 protein for breast cancer cells." (PMID 22693547, 2012). "Further we investigated the relationship between STARD13 and invasion potential in breast cancer cells by transwell migration assay with co-transfection of siRNA-STARD13, miR-125b mimics and siRNA-STARD13, miR-125b inhibitor and siRNA-STARD13 and NC group." (PMID 22693547, 2012). "For the first time, we identified STARD13 as a target of miR-125b and miR-125b would promote breast cancer cells migration via regulating STARD13 expression by a siRNA targeting STARD13." (PMID 22693547, 2012). "We validated that miR-125b promoted breast cancer metastasis in vivo and in vitro and that STARD13 was one of miR-125b targets was also validated in previous results." (PMID 22693547, 2012). "The STARD13-correlated ceRNA network was able to co-regulate each other by competing for numerous shared miRNA binding sites, resulting in the formation of a ceRNA network to suppress breast cancer metastasis and EMT coordinately." (PMID 39170516, 2024). "In addition, 3′UTRs of HOXD inhibited migration, invasion, and adhesion of breast cancer via serving as STARD13 ceRNAs." (PMID 37827698, 2023). "We then explored whether the miR-125b/STARD13 axis is responsible for the inhibition of Tanshinone IIA on breast cancer stemness." (PMID 35057866, 2022). "Importantly, our recent work demonstrates that the 3'UTR of STARD13 mRNA attenuates breast cancer stemness via hindering YAP/TAZ (transcriptional coactivator with PDZ-binding motif) activity through co-regulating Rho-GTPase/F-actin and Hippo signaling." (PMID 35057866, 2022). "Thus, we assume that this miR-125b/STARD13 axis enhances breast cancer stemness probably through RhoA and Hippo signaling, which should be further investigated." (PMID 35057866, 2022). "Notably, miR-125b overexpression enhanced the stemness of breast cancer cells, and miR-125b overexpression or STARD13 knockdown impaired the inhibitory effects of Tanshinone IIA on the stemness of breast cancer cells." (PMID 35057866, 2022). "Tanshinone IIA could attenuate the stemness of breast cancer cells via targeting the miR-125b/STARD13 axis." (PMID 35057866, 2022). "Furthermore, we indicated that Tanshinone IIA suppressed breast cancer cell stemness in an miR-125b/STARD13 axis-dependent manner." (PMID 35057866, 2022). "STARD13 is a tumor suppressor that plays a role in breast cancer invasion and metastasis." (PMID 34797887, 2021). "Cdc42 is inhibited by StarD13 but it remains active at sites of invadopodia, where Cdc42 is required for activating nucleation promoting factors in a similar way to the spatial regulation described for RhoA and RhoC in breast cancer cells (model)." (PMID 32900380, 2020). "Furthermore, recent findings have revealed that StarD13 and its competing endogenous RNA, ceRNAs-3’UTRs inhibit breast cancer metastasis by inhibiting epithelial to mesenchymal transition (EMT)." (PMID 32900380, 2020). "Also, previous data in astrocytoma, breast cancer and colon cancer, suggested the role of StarD13 as a tumor suppressor in these cancers, while revealing a simultaneous positive regulatory role in cell migration." (PMID 32900380, 2020). "Indeed, StarD13 siRNA (both oligos) significantly increase cell invasion consistent with StarD13 role as a tumor suppressor as well as previously published findings in breast cancer cell model." (PMID 32900380, 2020). "However, recent evidence supports StarD13 being a tumor suppressor in breast cancer and that it regulates cell motility and invasion." (PMID 30899277, 2019).
breast cancer (continued). "In this work, we showed that STARD13-correlated ceRNA network could regulate CSC traits of breast cancer cells through two independent pathways, which collaboratively led to the nucleus-cytoplasm translocation of YAP/TAZ." (PMID 29848346, 2018). "We further evaluated whether STARD13-correlated ceRNA network regulates tumor-initiating potential of breast cancer cells in vivo." (PMID 29848346, 2018). "Finally, we indicated that STARD13-correlated ceRNA network enhanced doxorubicin sensitivity in breast cancer cells." (PMID 29848346, 2018). "We then asked whether STARD13-correlated ceRNA network modulates breast cancer cells stemness through LATS1/2." (PMID 29848346, 2018). "Functionally, we indicated that activating STRAD13-correlated ceRNA network inhibited CSC-related traits, i.e., tumor sphere formation and tumor initiation properties of breast cancer cells while depleting STARD13 or its ceRNAs promoted these CSC-related traits." (PMID 29848346, 2018). "It led us to speculate whether STARD13-correlated ceRNA network could also sensitize breast cancer cells to doxorubicin." (PMID 29848346, 2018). "Our previous study has shown that STARD13-correlated ceRNA network could inhibit breast cancer metastasis by suppressing EMT process." (PMID 29848346, 2018). "Our previous study uncovers that miR-125b could promote breast cancer metastasis by binding with STARD13 in vitro and in vivo, prompting us to explore whether some other transcripts may serve as STARD13 ceRNAs to coordinately suppress breast cancer metastasis." (PMID 26985770, 2016). "It's reported that transcripts within a ceRNA network are co-regulated, we then tested whether STARD13 ceRNAs exhibited concordant expression patterns with STARD13 in breast cancer cell lines and tissues with different metastatic potential." (PMID 26985770, 2016). "The surprising increase in StarD13 expression level in higher grades of breast cancer lead us to investigate whether StarD13 is indeed a tumor suppressor in our cells." (PMID 24627003, 2014). "We were then interested in investigating the role of StarD13 in breast cancer cell motility." (PMID 24627003, 2014). "Therefore, consistent with the literature, StarD13 seems to function as a tumor suppressor in breast cancer." (PMID 24627003, 2014). "We also showed that StarD13 has an anti-proliferative effect on breast cancer cells." (PMID 24627003, 2014). "STARD13 is lower expressed in breast cancer cell lines compared with normal cells." (PMID 22693547, 2012). "For instance, miR-125b may induce breast cancer metastasis by binding to STARD13." (PMID 35430805, 2022). "Thus, we confirm that STARD13-correlated ceRNA network could increase the sensitivity of breast cancer cells to doxorubicin in ceRNA-dependent." (PMID 29848346, 2018). "Therefore, STARD13- and its ceRNAs-3’UTRs might be used as combinatorial miRNA inhibitors for potential clinical applications, shedding fresh light on treatment of breast cancer." (PMID 26985770, 2016). "Given the crucial role of STARD13-, CDH5-, HOXD1-, and HOXD10-3’UTRs in breast cancer metastasis, we believe that STARD13-, CDH5-, HOXD1-, and HOXD10-3’UTRs could be therapeutic targets for the development of anti-metastatic strategy for breast cancer treatment in the near future." (PMID 26985770, 2016). "In addition, our previous studies suggest that miR-125b could contribute to breast cancer metastasis via binding with STARD13." (PMID 26985770, 2016). "However, StarD13 showed a relatively high expression in highly metastatic forms of breast cancer." (PMID 24627003, 2014). "In breast cancer cells, the 3′UTR of the STARD13 mRNA can act as a ceRNA that regulates stemness, EMT and metastasis." (PMID 39272915, 2024). "STARD13 3′UTR was also found to inhibit migration and invasion in breast cancer cells by upregulation of TP53INP1, a suppressor of metastasis, through competition for miR-125b binding." (PMID 39272915, 2024).